BKGD (beta-keto-L-gulonate decarboxylase)
Description:
Catalyzes the decarboxylation of 3-dehydro-L-gulonate to produce L-xylulose, used in the pentose pathway. Exhibits ester hydrolase activity on p-nitrophenyl acetate, in vitro. Regulates DNA damage and repair by regulating HIF1A degradation via chaperone-mediated autophagy (CMA). [Isoform 3]: Probably non-functional when tested on p-nitrophenyl acetate, in vitro.
Synonyms: C11orf54; PTD012; MEEP; PTOD012
Tractability: PROTAC: ubiquitination databases record sites on it; its protein half-life has been measured.
Gene: Protein-coding gene on chromosome 11 (93,741,570 to 93,767,202, forward strand). Ensembl gene ENSG00000182919.
Subcellular location: Nucleus; Cytoplasm
Subcellular location (Human Protein Atlas): Nuclear bodies; Nucleoplasm
Gene Ontology:
Molecular function: hydrolase activity, acting on ester bonds; protein binding; zinc ion binding; dehydro-L-gulonate decarboxylase activity
Biological process: DNA damage response; regulation of DNA repair
Cellular component: cytoplasm; extracellular exosome; nucleus
Genetic constraint (gnomAD): Loss-of-function variants: 21 observed, 28.61 expected, observed/expected ratio (o/e) 0.73, 90% interval 0.52 to 1.06. The upper end of that interval is the gene's LOEUF score, 1.06, which puts it in group 4 of 6, group 1 being the genes least tolerant of losing a copy. Missense variants: 320 observed, 330.86 expected, observed/expected ratio (o/e) 0.97, 90% interval 0.88 to 1.06. Synonymous variants: 96 observed, 108.97 expected, observed/expected ratio (o/e) 0.88, 90% interval 0.75 to 1.04.
Homologues: Orthologues: chimpanzee C11H11orf54 (99% identical), rabbit C11orf54 (92% identical), pig C11orf54 (92% identical), dog C11orf54 (90% identical), guinea pig C11orf54 (89% identical), mouse 4931406C07Rik (88% identical), rat C8h11orf54 (87% identical), zebrafish C5H11orf54 (63% identical), Drosophila melanogaster CG9119 (47% identical), Drosophila melanogaster meep (44% identical), Caenorhabditis elegans C24B5.4 (40% identical).
Diseases named in the same sentence as BKGD in open-access papers:
BKGD is named in the same sentence as 12 diseases in open-access papers, as found by Europe PMC text mining. Sharing a sentence is not in itself a finding about the gene and the disease.
BKGD shares sentences with these, for which no sentence is quoted: cancer (3 papers); clear cell renal cell carcinoma (2); tumor (2); colorectal cancer (1); endometrial cancer (1); Insulin resistance (1); Kidney Chromophobe (1); non-alcoholic fatty liver disease (1); Obesity (1); prostate carcinoma (1); renal carcinoma (1); renal cell carcinoma (1).